ALB (albumin)
Diseases named in the same sentence as ALB in open-access papers (continued):
Sharing a sentence is not in itself a finding about the gene and the disease.
lung cancer (continued). "The advanced lung cancer inflammation index (ALI) is a composite prognostic index that incorporates body mass index (BMI), serum albumin, and neutrophil-to-lymphocyte ratio (NLR), reflecting both nutritional and systemic inflammatory states." (PMID 40977978, 2025). "Despite its name suggesting lung cancer specificity, ALI integrates nutritional status (BMI and albumin) and systemic inflammation (neutrophil-to-lymphocyte ratio), making it potentially applicable across various cancer types." (PMID 40904509, 2025). "Another important factor that indicates an amelioration in body composition and inflammation status is the reduction of albumin, CRP, and triglycerides levels, indicating a remodulation of the microenvironment of lung cancer." (PMID 39652453, 2025). "The Advanced Lung Cancer Inflammation Index (ALI) combines body mass index (BMI), albumin, and neutrophil-to-lymphocyte ratio (NLR)." (PMID 40777182, 2025). "The Advanced Lung Cancer Inflammation Index (ALI), calculated as Body Mass Index (kg/m2) × Serum Albumin (g/dL)/Neutrophil-to-Lymphocyte Ratio, has been identified as a strong prognostic marker for overall survival in lung cancer patients." (PMID 40904509, 2025). "The Advanced Lung Cancer Inflammation Index (ALI) was calculated using body mass index (BMI), serum albumin levels, and the neutrophil-to-lymphocyte ratio (NLR)." (PMID 40233085, 2025). "The Advanced Lung Cancer Inflammation Index (ALI) is a measure that combines body mass index (BMI), serum albumin levels, and neutrophil-to-lymphocyte ratio (NLR) to show overall inflammation and nutritional status." (PMID 40777182, 2025). "The ALI, a composite biomarker combining BMI, serum albumin, and NLR, was initially developed as a prognostic tool in advanced lung cancer." (PMID 40791910, 2025). "Such as serum albumin (ALB) and globulin (GLB), lactate dehydrogenase (LDH), and electrolytes are widely used as predictive indicators for lung cancer." (PMID 39333995, 2024). "Specifically, albumin, age, and cancer staging are related factors that impact the occurrence of CRA in lung cancer patients with decreased serum iron." (PMID 38562035, 2024). "Surprisingly, we found participants with lung cancer tend to have higher concentrations of ALP and GGT and lower concentrations of ALB, ALT, AST, TBIL and TP in the blood." (PMID 39721983, 2024). "The results show that CRA in lung cancer is mainly related to serum iron, CRP, albumin, total cholesterol, KPS score, surgery, and chemotherapy (p < 0.05)." (PMID 38562035, 2024). "Based on BMI, serum albumin, neutrophil, and lymphocyte counts, ALI was initially widely utilized to assess the prognosis of advanced lung cancer as a novel biomarker of nutritional inflammation." (PMID 39606578, 2024). "Several previous studies have shown that perioperative albumin levels are significantly associated with postoperative complications, such as myocardial infarction, in patients with malignancies, including colorectal cancer, gastric cancer, and lung cancer, and in noncancer patients." (PMID 38773489, 2024). "In summary, chemotherapy, KPS score, serum iron, CRP, albumin, and total cholesterol are all factors related to CRA in lung cancer patients." (PMID 38562035, 2024). "Univariate analysis revealed statistically significant differences in the impact of age, gender, cancer staging, surgery, radiation therapy, CRP, albumin, and total cholesterol on the incidence of CRA in lung cancer patients with normal serum iron levels." (PMID 38562035, 2024). "The findings indicated that patients with favorable PS and high albumin levels experienced longer survival periods, even when opting for BSC as their lung cancer treatment approach." (PMID 39195131, 2024). "On the other hand, CRP, albumin, total cholesterol, and cancer staging are factors that impact the occurrence of CRA in lung cancer patients with normal serum iron." (PMID 38562035, 2024).
lung cancer (continued). "CRA in lung cancer is mainly related to surgery, chemotherapy, Karnofsky Performance Status (KPS) score, serum iron, C‐reactive protein (CRP), albumin, and total cholesterol (p < 0.05)." (PMID 38562035, 2024). "We recognize that the individual components of the NUn score—CRP, ALB, and WBC count—have been previously studied in the context of lung cancer prognosis." (PMID 39513125, 2024). "Recently, the advanced lung cancer inflammation index (ALI), a new inflammatory marker that is calculated as BMI (kg/m2) × albumin (g/dL)/NLR, was initially found to be a useful prognostic index in lung cancer." (PMID 36717809, 2023). "The advanced lung cancer inflammation index (ALI), including body mass index (BMI), albumin, and neutrophil to lymphocyte ratio (NLR), was a systemic inflammation index that was primarily applied in lung cancer patients." (PMID 38111710, 2023). "The platelet-to-lymphocytes ratio (PLR) and albumin multiplying lymphocytes, known as the prognostic nutritional index (PNI), have been extensively studied in lung cancer." (PMID 36980740, 2023). "The prognostic value of BUN to serum albumin ratio was reported in patients with Escherichia coli bacteremia, ICU patients with lung cancer, critically ill patients with acute pulmonary embolism, and patients with aspiration pneumonia." (PMID 35928140, 2022). "By manipulating magnetic albumin nanospheres, the MAIN significantly increased the adhesion and absorption of GLC-82 lung cancer cells overexpressing EGFR (MANs)." (PMID 36085575, 2022). "Albumin-bound paclitaxel (nab-PTX) is widely used in the treatment of breast and lung cancers due to its excellent therapeutic effects." (PMID 36595835, 2022). "A novel inflammation-related marker, advanced lung cancer inflammation index (ALI), calculated from albumin, NLR and BMI (BMI × ALB/NLR), has been identified for the first time as a valid prognostic indicator in metastatic non-small cell lung cancer (NSCLC)." (PMID 35729545, 2022). "This study also confirmed the relevant views that the decrease in the albumin level can significantly affect the prognosis of patients with lung cancer cachexia and validated the notion that the occurrence of hypoproteinemia may be related to the occurrence of cachexia in patients with lung cancer." (PMID 35898878, 2022). "When these factors were included in the multivariate COX analyses, we noted that sex, stage, albumin, ALI, surgery, and KPS score served as independent prognostic factors for patients with lung cancer cachexia." (PMID 35898878, 2022). "Albumin-bound paclitaxel (nab-PTX), a novel paclitaxel preparation, has been found to successfully blocks tumor progression in breast and lung cancer." (PMID 36595835, 2022). "In this retrospective study, we assessed the effect of BMI, ALB, serum creatinine and serum inflammatory markers such as LMR and PLR on survival outcomes in lung cancer patients receiving ICI treatments." (PMID 35902908, 2022). "Results showed that age, line, ALB, LDH, and MON can be applied as one of the criteria for patients of lung cancer to choose immunotherapy." (PMID 36540802, 2022). "For example, in lung cancer patients’ serum level alterations were documented for AGP, AAT, and ALB." (PMID 35174082, 2022). "Sex, stage, serum albumin, ALI, KPS score, and surgery served as independent prognostic factors for patients with lung cancer cachexia." (PMID 35898878, 2022). "The modified Glasgow prognostic score (GPS) comprising serum CRP, albumin, as well as CAR measurements, indicates prognostic value in several cancers, including lung cancer." (PMID 33434414, 2021). "Serum total SOD activity and SOD1, SOD2, albumin, CRP, and ceruloplasmin concentrations were determined in lung cancer patients (n = 190) and control subjects (n = 52)." (PMID 34832849, 2021).
lung cancer (continued). "The advanced lung cancer inflammation index (ALI), as a newly reported inflammation-based prognostic score, is based on body mass index (BMI), serum albumin (ALB), and neutrophil to lymphocyte ratio (NLR)." (PMID 31354887, 2019). "Recently, the advanced lung cancer inflammation index (ALI), which is based on the body mass index (BMI), serum albumin concentration and NLR, was developed as a prognostic marker in patients with lung cancer." (PMID 30885163, 2019). "We found that platelet, PCT, NLR and PLR, albumin, HDL, and CRP levels aided in lung cancer diagnosis and the detection of late-stage disease." (PMID 29941786, 2018). "A recent study described the prognostic significance of advance lung cancer inflammation index (ALI; a systemic inflammation-based index), which was calculated by multiplying body mass index (BMI, kg/m2) by the serum albumin/neutrophil-lymphocyte ratio (NLR)." (PMID 27706243, 2016). "We investigated the efficacy and safety of albumin-bound paclitaxel (nab-PTX) and carboplatin (CBDCA) with concurrent radiotherapy for unresectable locally advanced non–small-cell lung cancer (NSCLC)." (PMID 26442970, 2016). "Advanced lung cancer inflammation index (ALI, body mass index [BMI] x serum albumin/neutrophil-lymphocyte ratio [NLR]) has been shown to predict overall survival (OS) in small cell lung cancer (SCLC)." (PMID 27706243, 2016). "The Advanced Lung Cancer Inflammation Index (ALI), integrating body mass index, albumin, and neutrophil-to-lymphocyte ratio, reflects nutritional and inflammatory status, both of which may influence procedural outcomes." (PMID 42204452, 2026). "The advanced lung cancer inflammation index (ALI), which includes BMI, albumin, and neutrophil to lymphocyte ratio (NLR), was initially developed for lung cancer, but has since been applied to other cancers including esophageal, pancreatic, and gastric cancers." (PMID 40028227, 2025). "The objective nutritional indices, such as C-reactive protein-to-albumin ratio (CAR), advanced lung cancer inflammation index (ALI), prognostic nutritional index (PNI), geriatric nutritional risk index (GNRI), and controlling nutritional status (CONUT) score, were calculated." (PMID 41586234, 2025). "We employed untargeted adductomics to establish ROS adduct signatures in human serum albumin (HSA) from lung cancer cases and controls from never-smokers in the Shanghai Women’s Health Study." (PMID 40227422, 2025). "Another study investigating the association between inflammatory markers, including the SII and leukocyte-albumin ratio, and the comorbidity of COPD and lung cancer found that elevated levels of these markers were independent risk factors for lung cancer comorbid with COPD." (PMID 40454139, 2025). "This increases confidence in the generalizability of our findings that the Fearon consensus criteria, WLGS, NLR, albumin and PNI predict worse overall survival, time to disability and time to emergency or inpatient admission in lung cancer, renal cell cancer and melanoma." (PMID 39817619, 2025). "The Advanced Lung Cancer Inflammation Index (ALI), originally developed for lung cancer, synergistically quantifies nutritional-inflammation equilibrium through the formula: ALI = (BMI × albumin)/NLR." (PMID 40535131, 2025). "Briefly, human serum albumin (HSA) NCs were loaded with doxorubicin and modified with the apoptotic protein TRAIL (tumor necrosis factor-related apoptosis-inducing ligand) to maximize specificity for lung cancer cells." (PMID 38543241, 2024). "In the regression analysis of liver serum enzymes, ALT/AST, TP, albumin, ALT, and ALP, with the SUV max of lung cancer patients, a significant positive correlation is observed, with calculated regression correlation coefficients of R2 = 0.026, 0.024, 0.024, and 0.018, respectively." (PMID 38957833, 2024). "The average albumin levels for diabetic patients with lung cancer were 28.5 g/L and in the non-diabetic group they were 34.9 g/L (p < 0.001)." (PMID 37627906, 2023).
lung cancer (continued). "Among the lung cancer cases, two patients with malignant pleural effusion successfully removed HFNC after pigtail catheter drainages and treatment with albumin plus diuretics; one patient who experienced hemoptysis and aspiration was stabilized after medical treatment and weaned off HFNC." (PMID 38002067, 2023). "Other albumin nanospheres were co-loaded in SPION as a vector of anticancer genes, modified by adding the anti-EGFR ligand monoclonal antibody with cetuximab as a targeting agent for adsorption of pDONR233-IFNG, aiming at the lung cancer cell line GLC-82." (PMID 36085575, 2022). "first combined NLR, serum albumin level, and body mass index (BMI) into a unified advanced lung cancer inflammation index (ALI) and demonstrated its prognostic value in patients who had been diagnosed as having metastatic non–small-cell lung cancer (NSCLC)." (PMID 34660250, 2021). "Since the albumin-to-alkaline phosphatase ratio (AAPR) has shown promising prognostic prediction in cancer patients, the prognostic value of the AAPR was evaluated in a large cohort of 7077 lung cancer patients." (PMID 34885242, 2021). "lung cancer: albumin and globulin, sex, nonsmoker, absolute neutrophil count, theophylline use, route of admission, marriage, and hemoglobin." (PMID 33616544, 2021). "The ongoing oxidative and inflammatory disturbances in our cohort may also be demonstrated by the generally lower concentrations of albumin and higher CRP and ceruloplasmin concentrations in lung cancer patients compared to the control group." (PMID 34832849, 2021). "Among the remaining 8964 lung cancer patients, serum albumin and/or serum alkaline phosphatase measurements were not available in 1887 patients, and therefore these patients were excluded." (PMID 34885242, 2021). "The presence of C. difficile and its toxins was investigated in lung cancer patients experiencing diarrhea during chemotherapy including paclitaxel (PTX), nanoparticle albumin-bound paclitaxel (nab-PTX), docetaxel (DOC), tegafur-gimeracil-oteracil (S-1), or irinotecan (CPT-11)." (PMID 34336670, 2021). "The albumin-to-globulin ratio (AGR) and albumin–globulin score (AGS), the indicators based on ALB and GLB, have been proved to function well in the prognosis evaluation of lung cancer and liver tumor." (PMID 34616677, 2021). "Decreased serum albumin levels and elevated alkaline phosphatase levels alone have previously been found to comprise negative prognostic value in lung cancer." (PMID 34885242, 2021). "A newly developed prognostic marker, the ALI, which is based on the BMI, serum albumin concentration and NLR, was found to be a novel prognostic marker in patients with unresectable metastatic colorectal cancer as well as in patients with lung cancer." (PMID 30885163, 2019). "Furthermore, the albumin, HDL, and CRP levels differed significantly in advanced stage lung cancer patients." (PMID 29941786, 2018). "However, multivariate analysis revealed that albumin, rather than CRP, was more strongly associated with length of hospital stay in older male patients with lung cancer undergoing chemotherapy." (PMID 40786260, 2025). "The results show that whether CRA occurs or not in lung cancer patients with decreased serum iron is mainly related to albumin, age, and cancer staging (p < 0.05)." (PMID 38562035, 2024). "Moreover, the prognosis of lung cancer cachexia patients with advanced disease, male gender, low albumin level, low ALI, low KPS score, and a primary focus without surgical treatment is worse." (PMID 35898878, 2022). "Similarly, the advanced lung cancer inflammation index (ALI), which is a modification of NLR that includes albumin (ALB) and body mass index (BMI), has been developed and demonstrated to be a prognostic marker of poor survival in several cancers, including non-small cell lung cancer (NLSCL)." (PMID 36425070, 2022). "Besides, there was also a cohort study reporting nonsignificant results between albumin and lung cancer." (PMID 34041866, 2021).
lung cancer (continued). "In both lung cancer patients and those with malignant diseases other than lung cancer, to our best knowledge, however, no studies have been conducted comparing changes in body weight and serum albumin levels between patients with and without FN." (PMID 33324729, 2020). "Similarly, Toc, a form of vitamin E, acts as an antioxidant but may not have a strong impact on the pathophysiology of lung cancer compared to other biomarkers like albumin, MUFAs, or lactate." (PMID 40719999, 2025). "Indeed, patients with albumin levels of ≥3.0 and those with a favorable performance status (PS of 0 or 1) might experience extended survival periods, even if they opt for BSC as their lung cancer treatment strategy." (PMID 39195131, 2024). "In addition, whether age, LDH, line, ALB and MON have predictive value in other treatment options for lung cancer patients also needs to be further explored, which can further determine the specific correlation of age, LDH, line, ALB and MON with immune response and inflammation." (PMID 36540802, 2022). "Indeed, the addition of albumin rescued cell viability in the absence of glucose and serum, suggesting that lung cancer cells may internalize extracellular protein and use it as a metabolic fuel when glucose is unavailable." (PMID 30609754, 2019). "There were no statistical differences between lung cancer patients and normal controls in aspartate aminotransferase (AST), alanine aminotransferase (ALT), albumin (ALB), fasting blood glucose (FBG), and serum creatinine (Cr) (P > 0.05)." (PMID 37980468, 2023). "ANC had statistically significant negative weak correlation with albumin concentrations (r = ‐0.154, P = 0.026), and MPV had statistically significant negative weak correlation with total protein concentrations (r = ‐0.153, P = 0.027) in lung cancer patients." (PMID 32377267, 2020).